TSG101 (tumor susceptibility 101)
Diseases named in the same sentence as TSG101 in open-access papers (continued):
Sharing a sentence is not in itself a finding about the gene and the disease.
lymph node metastasis (1 paper, 2014). "The univariate Kaplan-Meier analysis showed that positive TSG101 and PEG10 expression, and differentiation, tumor size, TNM stage, lymph node metastasis, invasion and surgical curability, is closely associated with a decreased overall survival in SC/ASC and AC patients (P<0.05 or P<0.001)." (PMID 24944680, 2014). "It was demonstrated that positive TSG101 and PEG10 expression were significantly associated with large tumor size, high tumor-node-metastasis (TNM) stage, lymph node metastasis, invasion and no resection (only biopsy) of SC/ASC and AC." (PMID 24944680, 2014).
mastitis (1 paper, 2025). Inflammation of breast tissue during lactation or postpartum due to an obstructed duct or infection. "Three types of EVs (C-EVs, M-EVs, and CM-EVs) isolated from colostrum, mature milk, and clinical mastitis milk had similar double-layer membrane morphology consistent expression of marker proteins HSP70, TSG101, and CD63, but disparate particle diameters." (PMID 39953606, 2025).
medulloblastoma (1 paper, 2025). A malignant, invasive embryonal neoplasm arising from the cerebellum. "Proteins commonly found in exosomes and microvesicles, namely, CD63, Alix, Flotillin-2 and TSG101, were present in EVs isolated from both non-treated and cisplatin-treated SHH and group 3 medulloblastoma cells and their corresponding whole cell extracts." (PMID 40495204, 2025).
metastatic disease (1 paper, 2023). "The presence of EV was confirmed on western blot by the presence of EV-enriched proteins CD9, CD63, CD81 and TSG101 in SEC fractions 7 to 10 isolated from a healthy control and a patient with metastatic disease." (PMID 37046768, 2023).
metastatic melanoma (1 paper, 2020). A melanoma that has spread from its primary site to another anatomic site. "Moreover, western blot analysis of exosomal markers Alix, TSG101 and CD9 on plasma samples of four metastatic melanoma patients from the WT cohort confirmed that PA isolates EVs from these samples." (PMID 32978468, 2020).
myoma (1 paper, 2012). "The present in vitro myoma and collagen assays showed a high expression of exosomal-associated markers (i.e., TSG101, TGF-β) in the HSC-3 cells and, to a lesser extent, in the stromal cells." (PMID 23342263, 2012).
nephrotic syndrome (1 paper, 2020). A collection of symptoms that include severe edema, proteinuria, and hypoalbuminemia; it is indicative of renal dysfunction. "In the present study, we investigated the excretion of UE-AQP2 in nephrotic syndrome using rats treated with puromycin aminonucleoside (PAN), as well as the release of exosomal marker proteins, including tumor susceptibility gene 101 protein (TSG101) and ALG-2 interacting protein X (ALIX)." (PMID 32560242, 2020).
ocular toxoplasmosis (1 paper, 2024). Ocular toxoplasmosis is an infection in the eye caused by the parasite, Toxoplasm a gondii. "All plasma samples from patients with ocular toxoplasmosis and cataract were positivefor the tetraspanins CD63 and TSG101." (PMID 39109736, 2024).
prostate adenoma (1 paper, 2017). "Royo and co-workers could also observe different TSG101 levels in different samples from prostate adenoma patients with relatively equal CD63 protein levels, considering different exosomal protein loading as a possible reason." (PMID 28859135, 2017).
renal cell carcinoma (1 paper, 2019). "The tumor susceptibility gene 101 (TSG101) is closely associated with various tumor types, but its role in the pathogenesis of renal cell carcinoma (RCC) is still unknown." (PMID 30675171, 2019).
Sepsis (1 paper, 2024). Sepsis is defined as life-threatening organ dysfunction caused by a dysregulated host response to infection. "Biomarkers of sEVs (CD63, CD9, CD81, Alix, and Tsg101) isolated from healthy control subjects and patients with sepsis were detected using western blotting." (PMID 38910259, 2024). "Heatmaps revealed that the expression levels of CD63, CD9, CD81, Tsg101, EEA1, Rab5, and Rab7 in lung macrophages were significantly higher than those in neutrophils in the healthy control sEV group and sEVs from patients with sepsis." (PMID 38910259, 2024).
spastic ataxia (1 paper, 2021). "Here, we demonstrate that vacuolar protein sorting-associated protein 13D (VPS13D), loss-of-function mutations of which cause spastic ataxia, coordinates FA trafficking in conjunction with the endosomal sorting complex required for transport (ESCRT) protein tumor susceptibility 101 (TSG101)." (PMID 33623047, 2021).
ZIKV infection (1 paper, 2024). "We also found that monocyte ZIKV infection induced tetraspanin CD63 internalization and translocation of tetraspanin CD81 and ESCRT-associated proteins TSG101 and Alix to the plasma membrane." (PMID 38247836, 2024).
tumor (103 papers, 1999 to 2025). "The Tumor Susceptibility Gene 101 (TSG101) encodes a protein with versatile functions in various molecular and biological processes that are essential for cell growth and survival." (PMID 40624726, 2025). "Fractions E2–E5 stained positively for the exosome-specific protein markers CD9 (27 kDa) and Tumour Susceptibility Gene 101 (TSG101; 44 kDa)." (PMID 40748658, 2025). "Other established small EV markers such as the programmed cell death 6 interacting protein (PDCD6IP or ALIX) and the tumor susceptibility marker TSG101 known for its role in vacuolar sorting and small EV biogenesis were also detected." (PMID 40440285, 2025). "Nevertheless, together our results provide new insights into the mechanisms underlying MOID and also sugget that future development of TSG101 as well as MAD2 inhibitors can be an effective therapy for killing MAD2-overexpressing tumor cells." (PMID 39551802, 2024). "For example, deletion of HRS, ESCRT-0 subunit STAM1 (signal transduction adapter molecule), and TSG-101 (tumor susceptibility gene 101) have been reported to reduce exosome release from tumor cells." (PMID 38983854, 2024). "TSG101 was originally defined as a tumor susceptibility gene and later characterized to be a core component of the ESCRT-I complex, and functions in the vacuolar protein sorting pathway involved in trafficking targets for lysosomal degradation." (PMID 37224147, 2023). "With proteomic approach to identify capsid protein (HBc) associated host factors and siRNA screen, we uncovered tumor susceptibility gene 101 (TSG101)." (PMID 37224147, 2023). "Expression of the well-accepted exosome marker proteins, CD9, CD63, and Tumor Susceptibility Gene 101 (TSG101), were identified by western blot." (PMID 36697384, 2023). "Recent studies have demonstrated that the tumor susceptibility gene TSG101 binds to and enhances GR transcriptional activity and similarly, PARP1 drives enzymatic activity for DNA damage-induced IKK-NF-κB activation." (PMID 37087471, 2023). "As a component of Endosomal Sorting Complex Required for Transport (ESCRT) complex I, the tumor susceptibility gene 101 (Tsg101) carries out multiple functions." (PMID 35768997, 2022). "Following the ISEV2018 guidelines, the EV characterization showed the presence of the EV-specific markers: CD9 molecule (CD9), CD81 molecule (CD81), and Tumor Susceptibility 101 (TSG101) in our serum." (PMID 35659238, 2022). "These analyses showed substantial enrichment of the multivesicular body marker TSG101 (tumor susceptibility 101) and cell surface marker CD9." (PMID 36612172, 2022). "Exosomes were confirmed by the expression of exosome marker, the tumor susceptibility gene (TSG101), while MMP14 was detected in the portion of exosome pellets, but not in the supernatant." (PMID 35223528, 2022). "Western blot was used to identify the EVs classical marker of Tumor Susceptibility Gene 101 (TSG101), and measure the amount of osteocyte‐specific protein Dentin Matrix Protein 1 (DMP1) in plasma EVs." (PMID 35508803, 2022). "In a genome‐wide screening for components of the dsDNA‐break‐induced IKK‐NF‐κB pathway, we identified scores of regulators, including tumor susceptibility gene TSG101." (PMID 36124865, 2022). "To this end, we decided to silence the expression of TSG101 (Tumor Susceptibility Gene 101), an essential component of the Endosomal Sorting Complexes Required for Transport-I (ESCRT-I) complex using shRNAs." (PMID 34072942, 2021). "The most highly expressed TSG101 splice variant in human tumor tissues is TSGΔ154-1054, which results in a deletion of nucleotides 154 to 1054." (PMID 34440370, 2021). "The long latencies in tumor formation in this model led us to conclude that TSG101 possesses weak oncogenic properties associated with cancer initiation." (PMID 32075127, 2020). "The tumor susceptibility gene 101 (TSG101) is located in chromosome 11p15 and encodes a 46 kDa protein of 390 amino acid residues." (PMID 30675171, 2019).
tumor (continued). "TSG101 deficiency in primary embryonic fibroblasts and tumor cell lines causes cell cycle arrest at the G1/S transition." (PMID 30759747, 2019). "For example, for mammalian ESCRT-I, there are single genes for the VPS23 [also called TSG101 (tumour susceptibility gene 101)] and VPS28 subunits, but four variants of VPS37 (VPS37A–D) and three variants of MVB12 (MVB12A/B and UBAP1)." (PMID 30190330, 2018). "Specifically, a TSG101 splicing variant missing nucleotides 154 to 1054 (TSGΔ154-1054), which is linked to progressive tumor-stage and metastasis, has puzzled investigators for more than a decade." (PMID 26811492, 2016). "The TSG101 splice variant, which harbors a deletion of nucleotides 154 to 1054 (designated TSGΔ154-1054), is the most commonly expressed in human tumor tissues." (PMID 26811492, 2016). "We detected tetraspanin proteins (CD9, CD63, CD81), Alix and tumor susceptibility gene-101 (TSG101) of exosomal markers from rotenone treated CSCs." (PMID 25682864, 2015). "The Tumor Susceptibility Gene 101 (Tsg101) encodes a multi-domain protein that mediates a variety of molecular and biological processes including the trafficking and lysosomal degradation of cell surface receptors." (PMID 22479596, 2012). "The Tumor Susceptibility Gene 101 (Tsg101) was originally identified in transformed NIH3T3 cells using a random antisense knockdown approach." (PMID 22479596, 2012). "TSG101 (tumor susceptibility gene 101) is implicated in exosome biogenesis and intracellular trafficking, both of which are critically involved in intercellular communication within the tumor microenvironment." (PMID 40952239, 2025). "The EV amounts evaluated with EV-specific marker protein levels, apoptosis-linked gene 2-interacting protein X (Alix), tumor susceptibility gene (TSG101), and syntenin, in the purified EV fractions were also synergistically increased by adiponectin and roxadustat." (PMID 38351156, 2024). "In addition, the results of western blot revealed the expression of exosome specific marker proteins CD63, CD9, TSG101 (tumor susceptibility gene) in the supernatant of MDA-MB-231 cells, which further confirmed the presence of exosomes in BC cell supernatant." (PMID 37056561, 2023). "However, TSG101 was also identified as a tumor-suppressor gene and loss of TSG101 is involved in oncogenesis." (PMID 37371512, 2023). "AKTIP has similarity with the tumor susceptibility gene TSG101." (PMID 36096808, 2022). "Furthermore, the expression of the typical markers including heat shock protein 70 (HSP70), CD63, and tumor susceptibility hum 101 (TSG101) were detected by WB analysis." (PMID 34838052, 2021). "Finally, we studied the expression of GluAp and extracellular vesicles markers Alix and tumor susceptibility gene (TSG101) in both fractions by immunoblotting." (PMID 28399178, 2017). "To explore the roles of TSG101 as a tumor susceptibility gene, we used RNAi to examine whether TSG101 is involved in tumor cell biological behaviors such as migration and invasion in HT1080 fibrosarcoma cells." (PMID 26608825, 2015). "Moreover, several recent studies demonstrate that loss of ept/tsg101 or Rabex-5, two endocytic tumor suppressor genes, also induced JAK/STAT signaling activation and tissue overgrowth." (PMID 25923769, 2015). "Tumor susceptibility gene 101 (TSG101) was initially identified in fibroblasts as a tumor suppressor gene but subsequent studies show that TSG101 also functions as a tumor-enhancing gene in some epithelial tumor cells." (PMID 26608825, 2015). "In addition to its essential role in the MVB pathway, the role of Tsg101 in cytokinesis has also been associated with the tumor suppressor gene BRCA2." (PMID 24641493, 2014). "Despite a wealth of information about these proposed intracellular functions of the Tsg101 protein, it is still a conundrum why a knockout of the mammalian Tsg101 gene causes cell cycle arrest and cell death instead of accelerated growth and tumor formation." (PMID 22479596, 2012).
tumor (continued). "Finally, AKTIP has sequence similarities with the protein TSG101, a tumor susceptibility gene." (PMID 36096808, 2022). "This suggested role may provide a molecular mechanism by which TSG101 could act as a tumor suppressor, and it was reported that ‘TSG101-deficient’ SL6 cells exhibited alterations in EGF trafficking that may have caused elevated levels of active MAP kinases following EGF stimulation." (PMID 32075127, 2020). "The expression levels of CD9 and TSG101 proteins were significantly present in the serum of tumor patients and healthy subjects." (PMID 40636359, 2025). "Several studies have identified tumor-derived EVs carrying proteins such as CD9, tumor susceptibility gene 101 (TSG101), and heat shock protein 70 (HSP70) as potential biomarkers for GBM classification and prognosis." (PMID 40647449, 2025). "Next, we collected tumor specimens from animals that were treated with Dox for 72 h to investigate the immediate impact of the downregulation of TSG101 on cytokine and receptor tyrosine kinase signaling." (PMID 40624726, 2025). "Transgenic female mice that overexpress TSG101 under the Whey acidic protein (Wap) promoter in the mammary gland (WAP-TSG101) exhibited a higher incidence of sporadic tumor formation." (PMID 40624726, 2025). "The ligand-controlled downregulation of exogenous TSG101 in established carcinomas led to tumor regression." (PMID 40624726, 2025). "In contrast, EVs (size range of 70–120 nm, marker proteins CD9,CD63,TSG101) secreted by glioma-derived M2 macrophages inhibit the growth and invasion of tumor cells through the PI3K/AKT/mTOR signaling pathway." (PMID 39165926, 2024). "Western blot analysis showed that tumor cell-derived MVs expressed characteristic marker proteins TSG101 and CD63, along with high levels of EphA2." (PMID 38433190, 2024). "CC cells were treated with HEK293-derived exosomes (size range of 118–129 nm, marker proteins CD63, TSG101) containing miR-22 which enhance the radiosensitivity of tumor cells." (PMID 39165926, 2024). "The ability of TSG101 to have both pro- and anti-tumor effects places it among proteins that can regulate the cell cycle in opposing ways depending on the physiological context." (PMID 38607019, 2024). "This will be a challenge in the therapeutic development of anti-tumor and anti-virus drugs targeting TSG101." (PMID 35269659, 2022). "For example, the loss of HRS, signal transducing adapter molecule 1 (STAM1), and TSG101 reduces exosome secretion in multiple cell types such as tumor cells and dendritic cells." (PMID 36076942, 2022). "A variety of aberrant messages are generated upon the alternative splicing of TSG101 in tumor cells." (PMID 35269659, 2022). "After sacrificing, tumor weight and diameter were decreased in mice treated with miR-KD and TSG101-KD while increased in those treated with miR-OE." (PMID 33829013, 2021). "Tsg101 is considered to be a tumor suppressor as its functional inactivation has been shown to promote metastatic tumors in mice." (PMID 34440370, 2021). "While several reports suggest a role for this gene in tumor suppression, other complex and fundamental roles for Tsg101 in cells have been uncovered, ranging from endolysosomal maturation, cytokinesis, cell proliferation, and survival." (PMID 34271917, 2021). "Specifically, patients with high levels of circRNA_0000199 in CD63+/TSG101+ EVs EPs had high tumor recurrence and mortality rates underscoring the prognostic potential." (PMID 33158181, 2020). "As expected, compared with adjacent normal tissues, TSG101 mRNA expression was higher in RCC tumor tissues (p < 0.05)." (PMID 30675171, 2019). "Although TSG101 was initially found in a screen for potential tumor-suppressor genes in mouse, this product is one component of the ESCRT-I complex." (PMID 30759747, 2019).